CD4 (CD4 molecule)
Diseases named in the same sentence as CD4 in open-access papers (continued):
Sharing a sentence is not in itself a finding about the gene and the disease.
tumor (continued). "We first identified the CD4+ CTL subset as a unique subset of tumor-infiltrating immune cells in OSCC, characterized by a distinct gene expression pattern including the expression of cytotoxic genes through scRNA-seq analysis with strict quality control, TCR repertoire analysis and SCENIC analysis." (PMID 38077321, 2023). "These trials provide a rationale for the development of this approach in patients whose tumours have a high mutation frequency, particularly in combination with checkpoint blockade, and highlight the importance of CD4 T-cell recognition of tumours in combination with CD8 T-cell responses." (PMID 38567060, 2023). "CD4+-deficient mice lack the coverage of pericytes, suggesting that the immunosuppressive TME may have a significant effect on the formation of abnormal tumor vessels." (PMID 38193080, 2023). "To determine how the immune system could be modulated by IL1R1+ iCAFs, we further subclustered tumor myeloid and T cells of the Lee and Qian scRNA-Seq datasets to identify macrophages, CD4+ and CD8+ T cells as well as Tregs." (PMID 37460545, 2023). "Finally, in the analyses of the tumor microenvironments, tumors with high N1 scores showed more infiltrations of central memory CD4 T cells, mast cells and plasmacytoid dendritic cells." (PMID 37980411, 2023). "Furthermore, anti-CTLA-4 makes FOXP3+CD4+ Tregs alleviate their immunosuppressive activities and contribute to anti-tumor immune response." (PMID 36721212, 2023). "Furthermore, at the systemic anti-tumor immune response level, we had observed on the one hand – the enlargement of CD4+, CD8+ and NKT cell percentages among splenic leukocytes, and reduction in the size of Tregs population among CD4+ cells, on the other." (PMID 37033926, 2023). "Finally, we found that MEX3D was statistically related to tumour purity and positively related to CD4+ T cells, macrophages and neutrophils." (PMID 36507941, 2023). "Notably, CN2 and CN9 (pan-immune hotspots) were also associated with improved survival; analysis of cell dynamics revealed elevated numbers of CD4+ T cells in LTS tumours compared with STS tumours, which were enriched in both CN2 and CN9." (PMID 36725935, 2023). "In addition, we showed that CDK1/PBK/CHEK1 overexpression promotes GBM tumor aggressiveness, immunosuppression, and progression by recruiting the tumor-promoting immune cells such as the T Cells CD4+ Th2 subtype, MDSCs, and the TAM-M2 subtype." (PMID 38003585, 2023). "CD134+CD4+ T cells may play an essential role in improving the anti-tumor effect and the treatment response of ICIs." (PMID 36960067, 2023). "Naïve CD4+ T cells can differentiate into various effector cell lineages, such as Th1, Th2 and Th17 cells, which secrete different effector molecules and thereby characteristically shape the tumor microenvironment (TME) and the prognosis of cancer patients." (PMID 37346034, 2023). "Importantly, the elevated and specific expression of STAT4 was observed in T cells, and further minor annotations implied that STAT4 was expressed in multiple anti‐tumor T‐cell subtype: CD4+ T cells, CD8+ T cells, NK T cells, NK cells, and cycling T cells." (PMID 38107057, 2023). "Immunotherapy with monoclonal antibodies blocking the interaction between the receptors and their ligands in the tumor itself or in the draining lymph node has been shown to enhance priming of anti-tumor CD4 and CD8 T cells and to release TILs from inhibition in animal models as well as in human." (PMID 36261539, 2023). "In addition, we used other algorithms to evaluate the relationship between VEGFA expression and the infiltration of immune cells, including CD8+ T cells, CD4+ T cells and regulatory T cells, in various tumours." (PMID 36729917, 2023).
tumor (continued). "Whereas depletion of either CD8+ or CD4+ T cells alone did not affect treatment efficacy of olaparib and AZD1775 suggesting that the cytotoxicity of both CD8+ and CD4+ T cells is essential for the anti-tumour efficacy of combined PARP and WEE1 inhibition in the BRCA1/2 wild-type AT3OVA TNBC model." (PMID 37582853, 2023). "However, in the last years, increasing evidence suggests that CD4+ T cells also play a very important role in tumor immunity." (PMID 36980536, 2023). "The conversion of naïve CD4+ T cells to Tregs is a central process in tumor immune evasion." (PMID 37935952, 2023). "This may explain why CD4+ T cell depletion improved T cell activation and promoted tumor regression upon anti-PD-L1 therapy." (PMID 36969495, 2023). "We found that tumor cells expressing MHC class II molecules may be directly eliminated by CD4+ CTLs, potentially via degranulation and perforin release or activation of the TRAIL–TRAIL receptor axis." (PMID 38077321, 2023). "Furthermore, for these cytotoxic CD4+ T cells to recognize and kill tumor cells, not only must the tumor cell express MHC-II, but also the relevant antigens must be directed to the appropriate presentation pathway." (PMID 36512410, 2023). "In addition, Regulatory naive CD4+ T-cells impair cancer immunosurveillance by creating an immunosuppressive environment, thereby promoting tumor progression." (PMID 37301543, 2023). "In addition to the PD-L1/PD-1 pathway, other immune cells (CD8, CD4, FoxP3) appear to be exciting as tumor markers in the overall context." (PMID 37932810, 2023). "However, recent studies also highlight a prominent role of CD4+ T cells in the setting of tumor control (discussed in)." (PMID 37727790, 2023). "Pharmacological inhibition of NLRP3 inflammasome in HNSCC mouse models significantly reduces the IL-1β production, which reduces MDSCs, regulatory T cells (Tregs) and tumor-associated macrophages (TAMs) but increases CD4 and CD8 T cells in tumors to improve anti-tumor immunity." (PMID 36742298, 2023). "We observed that CD4+ and CD8+ T cell populations both exhibited increased secretion of interferon (IFN)-γ, tumor necrosis factor (TNF)-α, and interleukin (IL)-2, which are associated with anti-tumor activities." (PMID 36915911, 2023). "However, mice treated with Ad.P60 exhibited a significant lower number of tumor infiltrating Tregs (CD45+CD4+Foxp3-GFP+) than those administered with Ad.dT." (PMID 37766222, 2023). "In the present study, we found that CD4 + and CD8 + T cells distributed in different tumor areas were correlated with less aggressive tumor characteristics, but CRP distributed in different tumor areas were associated with more aggressive tumor features." (PMID 37277702, 2023). "In this study, Abrine and anti-PD-1 antibody were used to treat Hepa1-6 xenograft mice, results showed that both inhibited the expression of CD47 and PD-L1 in tumor tissues of mice, increased the levels of CD4+ and CD8+ T cells, decreased the level of Foxp3+ Treg cells." (PMID 37334368, 2023). "Both CD8 and CD4 T-cells up-regulate co-inhibitory receptors, which can inhibit T-cell function following the cross-linking of their ligands, entailing T-cell exhaustion and tumor escape." (PMID 37483605, 2023). "Furthermore, Stanczak and his coworkers reported an increase in tumor cell growth due to Siglec-9 upregulation on CD4+ and CD8+ T cell-bearing mice when compared to control mice in their study." (PMID 36109471, 2023). "Given the high proportion of CD4+ TILs exhibiting an effector memory phenotype (CD44HICD62L-) in intermediate and late-stage tumours (D14 & D21), these data suggest that as MC38 tumours progress, they are infiltrated by CD4+ effector subsets other than TH1 and TREG cells, likely TH2 or TH17 cells." (PMID 37153625, 2023). "However, the use of a single high dose CYC administration has been shown to eradicate tumor in a CD4+ T-cell dependent manner." (PMID 37681925, 2023).
tumor (continued). "However, in a study on PDAC, deletion of α-SMA+CAFs promotes tumor progression by increasing the number of CD4+ FOXP3+ Treg cells in tumors, suggesting that this subset has an important anticancer role in PDAC." (PMID 36759842, 2023). "Furthermore, as some of the tumor cells die, the overexpressed proteins can be taken up by APCs and presented to both CD4 & CD8 T cells." (PMID 37880313, 2023). "Furthermore, our T-cell depletion data showed that the efficacy of r4T1-MBTA vaccine’s efficacy against autologous tumor metastasis is T-cell dependent, with CD4 T cells playing a predominant role." (PMID 37434263, 2023). "In conclusion, the current study provided evidence that CPT treatment could potentially enhance the anti-tumour immune response in HCC patients through increasing the plasma levels of CD4, CD8, IL-2, IL-12, and IFN-γ after CPT administration." (PMID 37704828, 2023). "Importantly, the anti-tumor effect of 2FF was greatly reduced upon CD4 T cell depletion, suggesting an active role of the immune system in mediating the anti-cancer activity upon fucosylation inhibition." (PMID 36980181, 2023). "We found that the cancer cells could survive and develop a tumor, although the tumor samples with high immune scores were infiltrated with CD4+ T cells and CD8+ T cells." (PMID 36058633, 2023). "In conclusion, we demonstrate that Uro A effectively reduces primary tumor burden in a T cell–dependent manner, attenuates immunosuppressive M2-like TAMs, and significantly increases the infiltration of CD4+ and CD8+ T cells with a memory-like phenotype in the PDAC TME." (PMID 37448553, 2023). "Importantly, the Ubc9–/– mice manifested a similar proportion of tumor-infiltrating CD4+ T cells but a markedly higher proportion of intratumoral CD8+ T cells." (PMID 36626227, 2023). "Intravesical BCG infusion therapy, the primary treatment for NMIBC, may induce CD4+ T cell expansion to anti-tumor." (PMID 36960067, 2023). "In addition to CD8+ T cells, the pivotal role of CD4+ T cells in instigating and maintaining effective tumor immunity has been gaining recognition, even in the context of cancer immunotherapies tailored to induce a CD8+ CTL response." (PMID 38077321, 2023). "In this study, anti-tumor memory CD8 T-cells were more frequently identified than CD4 T-cells but lymph node or blood may be a better tissue to sample for these cells than spleen or peritoneum." (PMID 37033929, 2023). "Moreover, when agonists specific for the costimulatory molecules CD134 and CD137 were applied in mouse tumor models, eomesodermin (Eomes), which promotes the production of granzyme (Grm)B, was upregulated in CD4 CTLs." (PMID 36737819, 2023). "This discrepancy could be due to the use of Matrigel to inoculate tumor cells and the CD4−/− mouse model, which could alter the tumor microenvironment and disrupt the interactions occurring between CD4+ and CD8+ T cells during tumor initiation and progression." (PMID 36969495, 2023). "In addition, we observed that the CD4+ T cell in tissues was higher than that in blood, demonstrating the great potential of tumor infiltration of CD4+ T cells." (PMID 37889543, 2023). "Moreover, cryo-thermal ablation generated a long-lasting neoantigen-specific CD4+ T cell response that protects against tumor re-challenge." (PMID 37509365, 2023). "However, emerging research points to the capacity of CD4+ T-cells to exhibit cytotoxic capabilities under specific conditions, opening new avenues for our understanding of anti-tumor immunity." (PMID 37894816, 2023). "In addition, an in vivo study reported that the suppression of CD4+ T cells increased tumor metastasis and growth in an STK24-silenced mouse model of gastric cancer while enhancing the expansion of CD11b+Ly6C+ MDSCs and F4/80+ TAMs." (PMID 37202821, 2023).
tumor (continued). "Alternatively, IFNγ, and potentially other soluble factors, produced by vaccine-induced CD4 T cells may impact additional signaling pathways within tumors or other immune cell types to augment tumor killing." (PMID 37711623, 2023). "For example, the infiltration of CD4+/CD8+ T-cells into A3B-expressing tumor mass could be directly observed in clinical biopsies." (PMID 37190094, 2023). "The drawback of those serologic approaches is that it is uncertain whether the B cell responses occurred inside the tumor, or whether the antibodies displayed somatic hypermutation, which depends on help from CD4+ T cells." (PMID 37751306, 2023). "Notably, PD-1 acts as a tumor suppressor in CD4 T cells, but PD-1 checkpoint therapy significantly worsens disease progression in some but not all individuals with ATL." (PMID 36960072, 2023). "There is a growing interest in the role of CD4+ T cells in anti-tumor immunity." (PMID 37251920, 2023). "Flow cytometric analysis of the tumor‐infiltrated immune cells revealed an increased CD4+ cells, CD4+Pd1+ cells, a reduced CD11b+F4/80+ macrophages, and a trend of increased CD8+ cells, CD8+Ifnγ+ cells, CD8+Pd1+ cells, CD4+Ifnγ+ cells, and B cells in FIN56‐treated tumors." (PMID 37026630, 2023). "In addition, the ligation of PD-L1 on tumor cells to PD-1 on lymphocytes induces the apoptosis of tumor-specific T cells and promotes the differentiation of CD4+ T cells into forkhead family transcription factor 3 (Foxp3)+ Tregs." (PMID 37266424, 2023). "As for T cells CD4 memory activated, it was found that they mainly inhibit tumor growth." (PMID 37310469, 2023). "We found that the levels of infiltrating immune cells in 35 tumor types were significantly associated with NSUN2 expression, and the expression of NSUN2 was highly related to B cells, macrophages, CD4 T cells, neutrophils, CD8 T cells and dendritic cells (DCs) and most related to neutrophils." (PMID 37769000, 2023). "Th7R is a major component of CD4+ T cells in TILs and tumor-draining LNs." (PMID 37476074, 2023). "Furthermore, marrying tumor resection with therapy magnifies the expansion of tumor-specific T-cells, while peripheral blood CD4+ T-cells exhibit an enhanced shift towards activation and memory, augmenting the post-surgical anti-tumor reaction." (PMID 38106415, 2023). "However, regulatory T cells exhibit immunosuppression and CD4+ T cells become exhausted, which promote tumor progression and chronic viral persistence." (PMID 37829505, 2023). "In various primary tumors, through the prediction of the corresponding RNA signatures of multiple immune cells by bulk RNA sequencing and an RNA profiling algorithm, eosinophils, the abundance of such immune cells correlated with the abundance of resting memory CD4+ T cells in the primary tumor." (PMID 37508545, 2023). "In addition to MCC tumor cells, we observed clusters of immune cells including CD4-positive and CD8A-positive T cells (clusters 7 and 11) and CD68-positive macrophages (cluster 16)." (PMID 36719743, 2023). "The non-synonymous mutations in the tumor cell genome will produce non-autologous proteins (neoantigen) to activate the immune system by activating CD4+ and CD8+ T cells." (PMID 36761724, 2023). "Our study suggests that CD11bloCD172lo cDC2 in tumors might play important roles for activation of CD4+ and CD8+ cytotoxic T cells, and reduction of those cDCs might be reflected by tumor progression in Dnase1l3-deficient mice." (PMID 37581941, 2023). "The high affinity of peptides 17.1 and 17.1B to Hsp70 allows them to form stable complexes (17.1-Hsp70 and 17.1B-Hsp70) on the surface of Hsp70+ tumor cells and prevent CD4 + CD25 + lymphocytes from interacting with these cells, blocking the cytotoxic activity of these lymphocytes." (PMID 37511122, 2023). "However, evaluating the sub-populations, we did not observe significant differences in the frequency of CD8+ T cells or CD4+ FoxP3+ Tregs in the tumor." (PMID 36920329, 2023).
tumor (continued). "A recent study revealed that CD4+ T cells also could kill autologous tumor cells directly as cytotoxic immune cells in BLCA." (PMID 36960067, 2023). "Meanwhile, the CD4-positive T cells produce a variety of molecules such as proinflammatory cytokines, while NK cells promote tumor progression limitation also via releasing cytokines in the systemic circulation (indirectly) or directly (cytotoxic granules), aiming for cancer cell destruction." (PMID 37958547, 2023). "It is introduced to the patient’s immune system, causing the production and presentation of tumor antigens to CD8+ and CD4+ T cells, engaging both the innate and adaptive immunities and leading to the development of immunological memory in the case of tumor relapse." (PMID 37681891, 2023). "Interestingly, the combination of IL12-MSA and IL2-MSA led to an increased fraction of CD4+ T cells that were Tregs in the TdLN and spleen but a significantly decreased Treg fraction in tumor-bearing lungs." (PMID 37669107, 2023). "Notably, tumor control was largely retained in CD8-depleted mice but was completely abolished upon CD4 or combined CD4 and CD8 depletion." (PMID 37185301, 2023). "Moreover, the frequency of CD4+ or CD8+ T lymphocytes in the tumor-draining lymph node was further investigated by flow cytometry." (PMID 37061706, 2023). "T regulatory cell is a member of tumor infiltrating lymphocytes, which could suppress the immune response mediated by CD8+ and CD4+ T cells, thus linked to undesirable survival outcomes." (PMID 37702614, 2023). "Indeed, flow cytometric analysis revealed increased levels of tumor-infiltrating CD4+ and CD8+ T cells, which were further visualized by immunohistochemical staining." (PMID 36650153, 2023). "Furthermore, BGs loaded with tumor lysates significantly increased CD4+ and CD8+ T cell proliferation and IL-12p70 cytokine expression, leading to the efficient recognition of tumor-associated antigens." (PMID 37896250, 2023). "In addition, cytotoxic CD4+ T cells have been proven to directly induce tumor cell apoptosis, mediated by granzymes and perforin." (PMID 37829505, 2023). "In addition, other studies have found that STAT3 plays a major role in the expansion of regulatory T cells, and regulatory T cells can promote tumor progression by inhibiting the antitumor immune response mediated by TH1 CD4+ T and CD8+ T cells." (PMID 37724127, 2023). "Together, our work demonstrates that maca polysaccharides could enhance the anti-tumor effect when combined with 5-FU by regulating CD4+T cells, suggesting a novel potential immunomodulator in tumor therapy." (PMID 37274637, 2023). "The γδT cells represent a minor lymphocyte population (about 0.5–16% of total CD3+ cells) and, when isolated from patients with cancers, efficiently killed tumour cell lines, played a role at antigen-presenting cells (APCs) and induced CD4+ and CD8+ T cell proliferation and cytotoxicity." (PMID 37242569, 2023). "The peptides are assembled into peptide–MHC II complexes, which are delivered to the cell surface to be recognized by CD4+ T helper cells, triggering a specific T cell reaction and migrating to the tumor microenvironment to play an immune mechanism to inhibit tumor growth." (PMID 36851271, 2023). "The C2 subtype in this study was characterized by aberrant enrichment of prognosis-related SRGs with poorer prognosis and higher tumor-promoting cell infiltration, such as resting memory CD4 T cells, resting NK cells, and M2 macrophages, and higher immune and stromal scores." (PMID 37386521, 2023). "Notably, while depletion of CD8+ T cells partially abolished the immune memory induced by combination therapy, CD4+ T-cell depletion demonstrated a more significant effect on tumor growth than CD8+ T-cell depletion." (PMID 37291128, 2023).